IL34 (interleukin 34)
Diseases named in the same sentence as IL34 in open-access papers (continued):
Sharing a sentence is not in itself a finding about the gene and the disease.
systemic lupus erythematosus (9 papers, 2016 to 2025). An autoimmune multi-organ disease typically associated with vasculopathy and autoantibody production. "Researchers from Chongqing Medical University found that serum IL-34 is elevated in patients with systemic lupus erythematosus (SLE), which may be used as a diagnostic marker for SLE." (PMID 34095310, 2021). "Further mechanistic investigations using this lupus mouse model showed that IL-34 enhances intrarenal macrophage accumulation/proliferation, leading to macrophage-mediated RTEC apoptosis." (PMID 33072122, 2020). "NZB/W mice in this accelerated lupus model were treated with aCSF1, aIL34, or aCSF1/IL34, or with Cytoxan or aRW as controls to examine whether inhibiting macrophage/monocyte differentiation impacts proteinuria or survival." (PMID 31552020, 2019). "We measured the interleukin-34 (IL-34) level in sera from patients with systemic lupus erythematosus (SLE) and discoid lupus erythematosus (DLE) using an enzyme-linked immunosorbent assay (ELISA)." (PMID 29472590, 2018). "In people with systemic lupus erythematosus (SLE), IL-34 is expressed by tubular epithelial cells (TECs)." (PMID 34385542, 2021). "Therefore, elevated levels of IL-34 may be non-specific features of systemic inflammation and not a specific pathogenic factor of lupus." (PMID 29472590, 2018). "However, whether IL-34 is involved in the immunopathogenic process of systemic lupus erythematosus (SLE) is still unexplored in animal models and cell experiments." (PMID 28036035, 2016).
Arthritis (8 papers, 2014 to 2024). Inflammation of a joint. "A collagen-induced murine arthritis model study with additional IL-34 injection led to increased TNF-α and IL-17 mRNA expression in the synovial tissues, indicating a proinflammatory role for IL-34 via IL-17 production entailing aggravation of arthritis." (PMID 36530919, 2022). "Blockade of CSF1 alone or of both CSF1/IL34 for 9 weeks reduced arthritis compared to treatment with the aRW control and histologically, including a reduction of bone remodeling." (PMID 31552020, 2019). "Some of the newer cytokines such as IL-32, IL-34 and IL-35 are being investigated for their role in the pathogenesis and treatment of arthritis." (PMID 25561237, 2014). "Although the exact mechanism of the interaction between IL-34 and syndecan-1 remains elusive, it was shown that the lack of syndecan-1 impairs macrophage differentiation, ultimately attenuating murine IL-34-induced arthritis." (PMID 36530919, 2022). "Furthermore, the relatively newer cytokines such as IL-32, IL-34 and IL-35 are being investigated for their potential role in the pathogenesis and treatment of arthritis." (PMID 25561237, 2014). "Furthermore, IL-34 has been found to induce arthritis by promoting glycolysis expansion." (PMID 38481325, 2024). "Recent studies have shown a strong correlation between the synovial expression of IL-34 and factors such as rheumatoid factors, erythrocyte sedimentation rate, CRP, and the progression of arthritis on radiographic imaging." (PMID 38481325, 2024). "After 7 weeks of treatment, longitudinal arthritis clinical scores indicated that only dual blockade of CSF1 and IL34 or TNFRII-Fc treatments were protective in CIA." (PMID 31552020, 2019). "We report here that depending on the disease, single or dual blockade of IL34 and CSF1 is needed for controlling inflammation consistent with the concordant tissue-specific expression of both cytokines in diseases such as colitis or arthritis." (PMID 31552020, 2019). "In addition, several transcripts with known roles in arthritis were positionally enriched in specific joint locations including MMP1, MMP13, interleukin (IL) 1R, IL34 and CXCL12 (refs 17, 18, 19, 20)." (PMID 28332497, 2017). "CSF-1 or IL-34 stimulation of CSF1R promotes macrophage differentiation, activation and osteoclastogenesis, and pharmacological inhibition of CSF1R is beneficial in animal models of arthritis." (PMID 27036883, 2016). "Given that the expression of IL34 and CSF1 are both elevated in arthritis, and that CSF1R signaling is critical for macrophage differentiation and osteoclast homeostasis, we asked whether CSF1 and/or IL34 neutralization affected arthritis disease induction and outcome." (PMID 31552020, 2019).
gastric cancer (8 papers, 2019 to 2025). A primary or metastatic malignant neoplasm involving the stomach. "We conclude that IL-34 and IL-35 play distinct but significant roles in the pathogenesis of gastric cancer by modulating the tumour-friendly microenvironment through immune regulation." (PMID 40416985, 2025). "We have previously demonstrated that IL-34 is substantially suppressed in gastric cancer and that IL-34 is an independent biomarker for predicting the development of gastric cancer." (PMID 35347503, 2023). "Targeting the IL-34 and IL-35 pathways could offer a novel therapeutic strategy to improve outcomes in gastric cancer patients." (PMID 40416985, 2025). "However, our previous study demonstrates that IL-34 is inversely correlated with differentiation, metastasis and invasion of gastric cancer, which is rather controversial with our current discovery in HBV-HCC disease." (PMID 35347503, 2023). "The comparison of the observations in CRC and gastric cancer appear contradictory, since IL-37 is an anti-inflammatory cytokine, whereas IL-34 is a pro-inflammatory cytokine, yet these two cytokines both provide a protective role during the development of cancer within the gastrointestinal system." (PMID 35186997, 2022). "Our observation suggests IL-34 might be a potential biomarker for predicting the prognosis of gastric cancer patients." (PMID 32765828, 2020). "At this stage, our data demonstrate that IL-34 and its related markers M-CSF and TAM correlated well with prognosis of gastric cancer patients, particularly in the male gastric cancer patients." (PMID 32765828, 2020). "Although our data suggest that IL-34 and CD68+ TAM might be useful biomarkers in gastric cancer, other factors, for example, Epstein–Barr virus infection, are well known to be linked with gastric cancer." (PMID 32765828, 2020). "In addition, it remains to be clarified whether the suppression of IL-37 or IL-34 in CRC and gastric cancer, respectively, results in or from different stimuli, which requires further investigation." (PMID 35186997, 2022). "The discrepancy of IL-34 expression between HCC and gastric cancer may be related to the fact that these are different organ systems with almost completely different microenvironments, despite both liver and stomach being covered with epithelial cells and belonging to the digestive system." (PMID 36438052, 2022).
melanoma (8 papers, 2018 to 2026). A malignant, usually aggressive tumor composed of atypical, neoplastic melanocytes. "Compared with primary melanoma, elevated IL-34 expression is associated with increased CD163+ (an M2-polarization marker) macrophages in refractory metastatic melanoma." (PMID 36798830, 2023). "This contrasts with the expression pattern of this ligand‐receptor pair observed in melanoma, where it has been described that heightened expression of IL34 is related to lower immune cell frequencies, suggesting a more protumorigenic role." (PMID 41362277, 2026). "Han and colleagues described a clinical case of a patient with metastatic refractory melanoma that acquired resistance to anti-PD-1 immunotherapy and exhibited enhanced expression of IL-34 in refractory melanoma tissues." (PMID 36765929, 2023). "The most recent data in a case-control study found that a patient with refractory melanoma exhibited elevated IL-34 expression." (PMID 36798830, 2023). "Overall, while IL-34 plays a positive role in LC homeostasis under healthy conditions, its overexpression is positively correlated with melanoma persistence, TAM expansion and tumor proliferation." (PMID 33408768, 2021). "IL-34 should be considered as an essential target for further development of therapies against melanoma." (PMID 33408768, 2021). "IL-34 is highly expressed by tumor tissue in patients with melanoma, and its levels appear to depend on clinical status." (PMID 33408768, 2021). "We introduce for the first time a clinical case of a patient with metastatic refractory melanoma that acquired resistance to anti-PD-1 immunotherapy, showing an enhanced expression of IL-34 in refractory melanoma tissues." (PMID 29515691, 2018). "Immunohistochemistry staining of melanoma tissues showed an enhanced expression of IL-34 in metastatic refractory melanoma compared to primary melanoma tissues, which correlates with increased frequencies of CD163+ macrophages." (PMID 29515691, 2018). "As expected, Kaplan-Meier analysis of OS showed that high expression of IL34 significantly correlated with poor prognosis in melanoma (P = 0.038)." (PMID 29515691, 2018). "In this study, we evaluate the possible involvement of IL-34 in immunotherapy resistance of melanomas." (PMID 29515691, 2018). "Melanoma resection species were obtained from the patient, and utilized to compare IL-34 expression between primary and metastatic refractory melanoma." (PMID 29515691, 2018). "Melanoma resection species were obtained from a patient who developed a refractory melanoma against immunotherapy with Nivolumab, and stained with anti-IL-34, anti-melanoma antigens and anti-CD163 antibody." (PMID 29515691, 2018). "Tissue from a patient with Nivolumab-resistant metastatic melanoma showed a remarkable increase in expression of IL-34 compared with primary site melanoma tissues, and this upsurge in expression was demonstrated to be connected with greater frequencies of CD163, an M2 macrophage marker." (PMID 36798830, 2023). "Similarly, the RUNX1/CSF-1R/IL-34 axis was responsible for the tumor rebound in BRAF inhibitor resistant melanoma." (PMID 33408768, 2021). "Tumor areas were objectively judged by two independent researchers at 600× magnification for each section, and quantification of IL-34, melanoma antigens or CD163 immunoreactivity on the randomly-selected more than 20 tumor areas in each section was measured using FV1000 OLYMPUS software." (PMID 29515691, 2018). "From these results, we expected an impact for IL-34 expression on prognosis in melanoma patients." (PMID 29515691, 2018). "Consistent with these backgrounds, we found that high expression of IL-34 in refractory metastatic melanoma correlates positively with increased frequencies of CD163+ (a marker for M2-polarization) macrophages compared to primary melanoma." (PMID 29515691, 2018).
melanoma (continued). "Interestingly, immunohistochemistry staining showed remarkable enhancement of IL-34 expression in Nivolumab-resistant metastatic melanoma compared to melanoma tissues at the primary site." (PMID 29515691, 2018). "There is a report indicating that the canonical promoter of IL34, as well as of CSF1R, is rich in putative RUNX1 binding sites in melanoma." (PMID 33072227, 2020). "As a result, many studies are now using experimental animal models to determine whether or not inhibiting IL-34 in IL-34-producing melanomas may help overcome the therapeutic resistance issues." (PMID 36798830, 2023).
Obesity (8 papers, 2018 to 2025). Accumulation of substantial excess body fat. "IL-34 has been linked to obesity, chronic inflammation and insulin resistance, which in turn is associated with atherosclerosis." (PMID 36769623, 2023). "Liposuction led to a significant reduction of systemic INFα2 and IL-34, the latter being associated with obesity-related inflammation and other obesity-related pathologies." (PMID 36675759, 2022). "IL-34 is associated with obesity-induced inflammation and the pathogenesis of related diseases such as insulin resistance." (PMID 33805070, 2021). "Furthermore, IL-34 has been considered being associated with coronary artery disease, obesity and chronic inflammation." (PMID 30478377, 2018). "The reported relationship between VDD and IL-34 in the context of obesity and musculoskeletal disorders requires longitudinal and mechanistic studies." (PMID 41303570, 2025). "Together, our findings delineate a pathophysiological pathway: Obesity → VDD → IL-34 upregulation → bone and joint degeneration." (PMID 41303570, 2025). "This study provides new insights into the complex relationship between VDD, obesity, IL-34, OP and KOA." (PMID 41303570, 2025). "Furthermore, the possible mechanisms utilised by IL-34 in atherogenesis have been demonstrated via a linkage among IL-34, obesity, chronic inflammation, and insulin resistance, suggesting that IL-34 enhances atheroma via insulin resistance in obese patients." (PMID 34422917, 2021).
osteoarthritis (8 papers, 2012 to 2023). A noninflammatory degenerative joint disease occurring chiefly in older persons, characterized by degeneration of the articular cartilage, hypertrophy of bone at the margins and changes in the synovial membrane. "In patients with AS, we found serum levels of IL-34 were significantly elevated compared with those in patients with osteoarthritis, and in healthy controls, which suggests that IL-34 is associated with AS." (PMID 37551285, 2022). "SF levels of IL-34 correlated significantly with the symptomatic severity and radiographic of osteoarthritis of the knee." (PMID 37551285, 2022). "Given that IL-34 has been demonstrated to play dominant roles in synovial inflammation and bone erosion, it possibly led to RA and osteoarthritis (OA) pathology." (PMID 33947456, 2021). "We have already shown that IL-34 was elevated in RA synovial fluids compared to osteoarthritis (OA)." (PMID 25484525, 2014). "The production of IL-34 in FLS was up-regulated by TNFα in RA samples compared with osteoarthritis (OA) patients." (PMID 22264405, 2012). "TNF-α could induce the production of various cytokines (matrix metalloproteinases (MMPs) and IL-34) to participate in the inflammatory response of osteoarthritis by activating different signals." (PMID 36681837, 2023). "The AUC for IL-34 was 0.982 between patients with AS and patients with osteoarthritis." (PMID 37551285, 2022). "To understand whether IL34 and/or CSF1 have pathogenic roles in disease, we surveyed the expression of both in RA, osteoarthrosis (OA), and IBD." (PMID 31552020, 2019). "Patients with AS had significantly higher serum levels of IL-34 (878.9 ± 116.4, P < 0.01) and RANKL (155.6 ± 13.8 pg/mL, P < 0.01) than patients with osteoarthritis (626.6 ± 79.0 and 138.1 ± 15.3 pg/mL respectively) or healthy controls (612.9 ± 61.1 and 104.9 ± 15.4 pg/mL, respectively)." (PMID 37551285, 2022). "In patients with AS, serum levels of IL-34 (878.9 ± 116.4 pg/mL) and RANKL (155.6 ± 13.8 pg/mL) were significantly (P < 0.01) higher than those in patients with osteoarthritis (626.6 ± 79.0 and 138.1 ± 15.3 pg/mL, respectively) or a healthy group (612.9 ± 61.1 and 104.9 ± 15.4 pg/mL, respectively)." (PMID 37551285, 2022).
atherosclerosis (7 papers, 2016 to 2025). A disease characterized by the build-up of fatty material and calcium deposition in the arterial wall resulting in partial or complete occlusion of the arterial lumen. "Taken together, our results reveal the contribution of IL-34 to foam cell formation, which is the key initial process of atherosclerosis, provide a new clue to clarify the underlying mechanism of atherosclerosis, and suggest that IL-34 might be a new risk biomarker for atherosclerosis diagnosis." (PMID 30478377, 2018). "Interleukin-34 (IL-34) was recently reported to be a new biomarker for atherosclerosis diseases, such as coronary artery disease and vascular dementia." (PMID 39883639, 2025). "Elevated levels of IL-34 signal the involvement of inflammation, microvascular dysfunction, subclinical atherosclerosis, and endothelial damage in the pathogenesis of slow coronary flow (SCF)." (PMID 38166811, 2024). "Our results conclude that IL-34 facilitates foam cell formation by increasing CD36-mediated lipid uptake and suggest a potential new risk biomarker for atherosclerosis." (PMID 30478377, 2018). "More studies are needed to understand the contribution of IL-34 to foam cell formation and the pathologic processes of atherosclerosis, and to identify new opportunities for targeting this new cytokine for clinical benefit." (PMID 30478377, 2018). "This suggests that the newly identified IL-34 cytokine mediates distinct biologic activities and a potential link between atherosclerosis." (PMID 30478377, 2018). "In addition, macrophage, as an important cell type in the atherosclerosis, is also regulated by IL-34." (PMID 30050466, 2018). "Finally IL-32 and IL-37 may be protective while IL-34 may contribute to the development of atherosclerosis." (PMID 34422917, 2021). "In contrast, IL-34 may contribute to atherosclerosis, but its role in COVID-19 remains unclear." (PMID 34422917, 2021). "However, the role of IL-34 in atherosclerosis remains unknown." (PMID 30478377, 2018). "Overexpression of IL-34, along with elevated CRP serum level in atherosclerosis, suggests a possible link between IL-34 and foam cell formation." (PMID 30478377, 2018). "In addition, serum IL-34 level could probably be influenced by other unknown confounders or undetermined comorbidities, including some influential factors which could affect cardiac function or general condition, taking part in the process of atherosclerosis or cardiac remodeling in ICM." (PMID 30050466, 2018).
coronary artery disease (7 papers, 2016 to 2025). "This observational study demonstrates that in patients with chronic heart failure, increased serum levels of IL-34 were independently associated with the presence of kidney dysfunction and coronary artery disease, as well as their severity." (PMID 27982136, 2016). "On the other hand, our present study demonstrated that higher serum IL-34 levels were associated with more severe coronary artery disease, which is in accordance with the results of a previous study with limited sample size that including only those subjects who had CAD20." (PMID 27982136, 2016). "Interleukin 34 (IL-34), an additional ligand of colony stimulating factor-1 receptor (CSF-1R), has been identified as a biomarker of coronary artery disease (CAD) and chronic kidney disease (CKD)." (PMID 30050466, 2018). "Previous studies also showed that higher serum IL-34 levels were significantly related to more severe coronary artery disease (CAD) in patients with normal cardiac function as well as in patients with chronic HF." (PMID 30050466, 2018). "Serum IL-34 levels were significantly associated with the CAG Gensini score (r = 0.176, p < 0.001) on simple linear correlation analysis, indicating that patients with higher serum IL-34 levels tended to have more severe coronary artery disease." (PMID 27982136, 2016). "Therefore, IL-34 might not only be a biomarker for poor prognosis in patients with coronary heart disease, but also a target for reducing MI/R injury." (PMID 39883639, 2025). "Therefore, the present study aimed to analyze the association of IL-34 with comorbid conditions of HF, including chronic kidney disease (CKD) and coronary artery disease (CAD)." (PMID 27982136, 2016). "In order to determine the clinical significance of serum IL-34 in CHF patients, especially those with kidney dysfunction and coronary artery disease (CAD) comorbid conditions, serum IL-34 was measured in 510 consecutive patients with CHF in a cross-sectional study." (PMID 27982136, 2016). "Accumulating studies have revealed increasing serum levels of IL-34 in coronary artery disease (CAD) patients, and IL-34 can predict major adverse cardiovascular events in AMI patients, as well as the prognosis and severity of ischemic cardiomyopathy patients and ischemic stroke patients." (PMID 39883639, 2025).